ELF5 (E74 like ETS transcription factor 5)
Diseases named in the same sentence as ELF5 in open-access papers (continued):
Sharing a sentence is not in itself a finding about the gene and the disease.
breast cancer (continued). "Notably, key transcription factors involved in ER+ breast cancer were highly enriched, including methylation-sensitive estrogen response elements (EREs) and ELF5 (ETS transcription factor family members), as well as architectural proteins CTCF and ZNF165." (PMID 38182927, 2024). "ELF5’s role needs validation for practical use in breast cancer prevention and early detection." (PMID 38275872, 2024). "The ELF5 clock could provide a nuanced and biologically relevant framework for conducting breast cancer prevention trials, addressing many of the challenges associated with these types of studies." (PMID 38275872, 2024). "ELF5 is an important transcription factor for both normal breast and breast cancer development." (PMID 38275872, 2024). "Moreover, we found a negative association between high COMMD3 expression and tubule score, ELF5, c-Kit and AR expression in a large cohort of breast cancer cases." (PMID 37072858, 2023). "Repressive complexes may be recruited by negative regulators such as FOXC1 or other repressors, including the transcription factor ELF5, shown to repress ESR1 and a set of ERα-associated genes with promotion of basal-like breast cancer characteristics." (PMID 34831189, 2021). "In conclusion, acetylation of ELF5 at lysine residues might regulate its antiproliferative activity against breast cancer." (PMID 33742100, 2021). "Considering the different levels of ELF5 expression in breast cancer molecular subtypes, we speculated that acetylation might be involved in the modulation of ELF5 functions." (PMID 33742100, 2021). "It is conceivable that acetylation-dependent repression of Cyclin D1 expression might further contribute to the anti-proliferation activity of ELF5 in breast cancer." (PMID 33742100, 2021). "Moreover, ELF5 inhibits the transcription of Snail2/Slug and represses epithelial–mesenchymal transition in breast cancer metastasis." (PMID 33742100, 2021). "To determine if these effects of ELF5 could be seen in metastases from endocrine resistant breast cancer cases we interrogated gene expression profiles of matched primary and metastatic breast cancer from brain." (PMID 31895944, 2020). "For ELF5, both tumor promoting and suppressive roles have been reported in breast cancer." (PMID 32196521, 2020). "In breast cancer cells, ELF5 transcriptionally represses SNAI2 expression." (PMID 33158935, 2020). "This provides evidence that the effects of elevated ELF5 in MCF-7 cells also occur in three breast cancer metastases that have become resistant to endocrine therapy, consistent with elevation of ELF5 providing an additional mechanism driving acquired endocrine resistance." (PMID 31895944, 2020). "This provides a mechanism by which increased ELF5 expression could drive progression of ER+ breast cancer to become resistant to endocrine therapy." (PMID 31895944, 2020). "We used doxycycline-inducible expression of human ESE2B, the ELF5 isoform expressed in mammary gland, combined with ChIP-seq from MCF-7 and T47-D breast cancer cells, to search for a transcriptional mechanism that allows ELF5 to modulate estrogen-driven gene expression." (PMID 31895944, 2020). "ELF5 has been associated with differentiation of the luminal epithelium, and its expression is decreased significantly in luminal A, luminal B, and HER2 subtypes of breast cancer." (PMID 31248446, 2019). "ELF5 expression in a panel of breast cancer cell lines was analyzed by qPCR and Western blotting." (PMID 26738740, 2016). "Interestingly, however, while exogenous ELF5 localized to the nucleus in this study, cytoplasmic ELF5 staining is seen in some human breast cancer samples and is a predictor of outcome." (PMID 26738740, 2016). "In all breast cancer subtypes, there was a broader distribution of ELF5 isoform expression." (PMID 26738740, 2016).
breast cancer (continued). "Importantly, ELF5 levels rise when MCF7 luminal breast cancer cells acquire antiestrogen resistance, and resistant cells become dependent on ELF5 for their proliferation." (PMID 26717410, 2015). "Previous evidence has revealed a mechanism of Elf5 inhibiting EMT in breast cancer." (PMID 25629735, 2015). "In the mouse mammary tumor virus-Polyoma Middle T (MMTV-PyMT) model of luminal breast cancer, induction of ELF5 levels increased leukocyte infiltration, angiogenesis, and blood vessel permeability in primary tumors and greatly increased the size and number of lung metastasis." (PMID 26717410, 2015). "Up-regulation of the transcription factor ELF5 in tumors helps to create a micro-environment that recruits the innate immune system and increases vascular permeability, leading to increased metastasis in luminal breast cancer." (PMID 26717410, 2015). "In recent study, the Elf5–2b variant was distinguished as a major form of Elf5 expressed in human, so this isoform was chosen in our study as well as in another paper, in which Elf5 was demonstrated to be an inhibitor of EMT in breast cancer." (PMID 25629735, 2015). "We studied the immunogenicity of ER+ luminal breast cancer tumors in relation to Elf5." (PMID 26717410, 2015). "Analysis of human breast tumor data suggests that these processes also operate in ER+ breast cancer, and analysis of survival data shows this is prognostic in Luminal A cancers, with ELF5 expression in the cytoplasm clearly identifying a group of luminal A patients with early disease progression." (PMID 26717410, 2015). "Elf5 expression is greatly increased when MCF-7 breast cancer cells acquire Tamoxifen or Faslodex resistance by long-term exposure to these anti-estrogens, and these cells also become dependent on Elf5 for their proliferation, suggesting that Elf5 is a key determinant for anti-estrogen resistance." (PMID 25080108, 2014). "Taken together, the results in this study show that ELF5 is involved in the proliferation of breast cancer cells in culture, that ELF5 suppressed the estrogen-responsive phenotype in luminal breast cancer cells, and induced aspects of the basal phenotype in basal breast cancer cells." (PMID 23300383, 2012). "We hypothesize that the outcome of competing estrogen and ELF5 actions on a precancerous instance of the progenitor cell may play a significant role in determining the subtype of breast cancer that results." (PMID 23300383, 2012). "Luminal breast cancer cells that acquired resistance to the antiestrogen Tamoxifen showed greatly elevated levels of ELF5 and its transcriptional signature, and became dependent on ELF5 for proliferation, compared to the parental cells." (PMID 23300383, 2012). "To examine this hypothesis we manipulated the expression of ELF5 in basal and luminal breast cancer cell lines and examined the phenotypic consequences." (PMID 23300383, 2012). "ELF5 specified patterns of gene expression that distinguished the breast cancer subtypes." (PMID 23300383, 2012). "However these results are in contrast to expression analysis studies of breast cancer by other laboratories, which have suggested increased Elf5 expression in breast cancer." (PMID 20831799, 2010). "Consequently, the varied acetylation status of ELF5 may contribute to subtype-dependent outcomes in breast cancer proliferation influenced by ELF5 expression." (PMID 38275872, 2024). "Therefore, Cyclin D1 could act as an important downstream effector to mediate the suppressive role of ELF5 in breast cancer progression." (PMID 33742100, 2021). "Higher ELF5 expression in luminal A, but not B breast cancers, was broadly associated with the same five functional networks identified in the PyMT/Elf5 model: HGF and IL4, invasive phenotype, monocytes, immune system involvement, inflammation and the interferon response." (PMID 26717410, 2015).
breast cancer (continued). "Additionally, our data suggest that ELF5 may also be involved in the development of resistance to therapies designed to stop estrogen stimulation of breast cancer." (PMID 23300383, 2012). "ELF5 is a suppressor of EMT and metastasis through the transcriptional repression of Snail2 in breast cancer." (PMID 35186034, 2022). "In support of this view, a positive correlation between ELF5 and SIRT6 was found in 48 breast cancer clinical samples by immunohistochemical staining." (PMID 33742100, 2021). "In 2012 we proposed that luminal breast cancer cells may retain some of the cell-fate plasticity of the progenitor cell population seen in normal development, and that the expressed cancer phenotype results, at least in part, from the balance between ELF5 and ER influence." (PMID 31895944, 2020). "Here we report the result of a search for potential interactions between ELF5 and ER, using ChIP-seq, RIME and RNA-seq, in MCF-7 breast cancer cells, the model which alone has provided most of our understanding of the mechanisms of endocrine resistance." (PMID 31895944, 2020). "In a recent study, Elf5 emerged as a lineage regulator of mammary gland development and as an inhibitor of EMT in breast cancer via repressing Snail2/Slug." (PMID 31404945, 2019). "To further determine the effect of FOXC1 on Elf5 levels, we overexpressed FOXC1 in HC11 mouse mammary epithelial cells and T47D human breast cancer cells." (PMID 29070831, 2017). "Increased ESR1 expression in LEP driven by decline of ELF5 with age could be a possible mechanism to explain the increased ER expression in the normal breast with age, and may be relevant to the observation that the most common breast cancer subtypes in older women are ER+ luminal subtypes." (PMID 29016359, 2017). "A transcriptional network that operates in luminal breast cancer has been identified that promotes MDSC recruitment; this network is regulated by the ETS transcription factor ELF5." (PMID 28193698, 2017). "Three transcription factors, GRHL1, VGLL1, and ELF5 are strong candidates for the cell autonomous regulation of ST14/Prss14 in basal type ER− breast cancer patients and ER+ luminal A type breast cancer cell lines." (PMID 27167193, 2016). "AHR1 was reported to inhibit TGFβ-induced EMT; ELF5 inhibits Type I EMT in mammary gland development and Type III EMT in breast cancer by transcriptionally repressing SNAIL2." (PMID 26187636, 2015). "To study the relevance of ELF5 in metastasis in luminal breast cancer patients, we analyzed a cohort of ER+ HER2- tumors staining for ELF5 protein levels using IHC." (PMID 26717410, 2015). "Thus ELF5 provides a key transcriptional determinant of breast cancer molecular subtype by suppression of estrogen sensitivity in luminal breast cancer cells and promotion of basal characteristics in basal breast cancer cells, an action that may be utilised to acquire antiestrogen resistance." (PMID 23300383, 2012). "Three genes (FOXC1, EN1, and ELF5) stood out by displaying a pattern opposite to that of FOXA1, with hypomethylation and expression in Basal tumors, but hypermethylation and repressed expression in all other breast cancer subtypes." (PMID 40155623, 2025). "Based on the cBioPortal platform, we found that ELF5 expression was accompanied by gene alterations in multiple cancers such as uterine endometrioid carcinoma, breast cancer and colorectal cancer, but showed no alterations in renal cell carcinoma." (PMID 37980532, 2023).
breast cancer (continued). "ELF5 is an epithelial-specific member of the E26 transforming sequence (ETS) transcription factor family, which plays critical roles in malignancy, particularly in basal-like and endocrine-resistant forms of breast cancer." (PMID 33732284, 2021). "This was of particular importance considering that ELF5 not only acts as a tumor suppressor by inhibiting the transcription of ER, MYC and Slug in breast cancer but also acts as a carcinogenic factor in basal-like breast cancer cells and endocrine-resistant cells." (PMID 33742100, 2021). "ELF5 is a transcription factor regulating key genes e.g., FOXA1, EGFR, and MYC, and has been described as potential regulator of anti-estrogen resistance in luminal breast cancer and imatinib resistance in chronic myeloid leukemia." (PMID 32429253, 2020). "An ELF5 isoform switch has not been identified in breast cancer, in keeping with the present study, which showed an inconsistent pattern of isoform expression variation." (PMID 26738740, 2016). "In luminal breast cancer cells, a mutual negative-regulatory loop between ER and ELF5 occurs, which is dominated by ER and so keeps ELF5 levels low." (PMID 26717410, 2015). "Taken together, these results indicate that B-cell analysis does not model ELF5 action in luminal breast cancer." (PMID 26717410, 2015). "Conversely, ER- basal breast cancers are characterized by high ELF5 levels, while the stem-cell–like claudin-low subgroup does not express ELF5." (PMID 26717410, 2015). "Moreover, they display striking differences in transcriptomes and resemblance to clinical breast cancer subtypes upon over expression of the PRL mediator, ELF5." (PMID 25607819, 2015). "Together these data show that forced Elf5 expression reduced cancer cell proliferation, motility, invasion and mesenchymal characteristics, corresponding with reduced primary tumor growth in the MMTV-PyMT mouse mammary cancer model." (PMID 26717410, 2015). "Moreover, we demonstrated that selected genes from this subset (HES1, PRKCH, ELF5 and TM4SF1) did support invasiveness in ER+ breast cancer cells." (PMID 26356672, 2015). "Elf5 may directly inhibit the expression of the Snail transcription factor to further suppress the EMT and thereby reduce the invasiveness of breast cancer cells." (PMID 24959289, 2014). "Direct transcriptional targets of ELF5, which included FOXA1, EGFR, and MYC, accurately classified a large cohort of breast cancers into their intrinsic molecular subtypes, predicted ER status with high precision, and defined groups with differential prognosis." (PMID 23300383, 2012). "In the context of breast cancer, genes within the conserved signatures, such as those that characterize the more purified luminal progenitor subset (for example, KIT, CYP24A1, ELF5), have the potential to provide novel prognostic markers or therapeutic targets in breast cancer." (PMID 20346151, 2010). "It will be interesting to determine whether mammary-enriched ELF5, STAT5, NFIB, and GR are also recruited in these super-enhancers and whether differential molecular recruitment to super-enhancers determines the different breast cancer subtypes." (PMID 36232979, 2022). "Interestingly, these mammary tumors exhibited low expression levels of PRLR as well as other luminal and epithelial differentiation markers such as (Elf5, Muc1), claudins, and cell adhesion markers (Cdh1, Ocln), while showing elevated levels of EMT and BCSC markers." (PMID 33446633, 2021). "Furthermore, a higher expression of ELF5 was detected in triple-negative breast cancer than in luminal and her-2 positive breast cancer." (PMID 33742100, 2021). "Similarly, deleting Elf5 in the MMTV-neu (HER2) background increased EMT markers and the formation of lung metastases, while transgenic overexpression of Elf5 in the MMTV-PyMT model of luminal breast cancer inhibited cell proliferation." (PMID 30200227, 2018).
breast cancer (continued). "Interestingly, the binding site used by ELF5 to regulate MUC4 expression is the same site used by another Ets factor, PEA3, to regulate MUC4 expression in the pancreas, in HC11 mouse mammary epithelial cells and in MAT-B1 and MAT-C1 rat mammary tumour cells, suggesting some functional redundancy." (PMID 20949099, 2010).
COVID-19 (6 papers, 2022 to 2024). A disease caused by infection with severe acute respiratory syndrome coronavirus 2. "We determined that rs7949972 ELF5 (effect allele T) had a protective effect only in COVID-19 patients with a BMI <30." (PMID 39175753, 2024). "We were, however, able to replicate one of ten associations with COVID-19 hospitalization previously reported by the Human Genome Initiative43 (11-34528766-C-T, p = 0.03), which was linked to a role for ELF5, a transcription factor active in epithelial cells." (PMID 37327781, 2023). "The only association with evidence for a shared genetic signal with ELF5 expression and COVID-19 outcomes was seen for lung function (PP = 99%)." (PMID 35970849, 2022). "Upon analyzing the impact of the risk allele C rs7949972 ELF5 on TFs binding sites, we hypothesize that this allele may result in a more severe COVID-19 course." (PMID 39175753, 2024). "Another GWAS study in Thai suggested a protective effect of IL17B on 5q32 against disease, and a recent release from IHG showed that MUC5B and ELF5 on chr11 might be associated with immune system regulation in the lungs in the development of COVID-19." (PMID 36649279, 2023). "To derive a possible hypothesis of how ELF5 expression might be linked to severe COVID-19, we collated a list of candidate genes, that were either regulated by or co-expressed with ELF5." (PMID 35970849, 2022). "The transcription factor ELF5 (ELF5) shows robust and directionally consistent associations across different outcome definitions, including a >4-fold higher risk (odds ratio: 4.88; 95%-CI: 2.47–9.63; p-value < 5.0 × 10−6) for severe COVID-19 per 1 s.d." (PMID 35970849, 2022). "In the present study, we replicated associations of the rs17713054 SLC6A20-LZTFL1, rs17078346 SLC6A20-LZTFL1, rs12610495 DPP9 and rs7949972 ELF5 with severe COVID-19 within the Caucasian population of Central Russia." (PMID 39175753, 2024). "While ELF5 is known to be highly expressed in multiple tissues, we demonstrated that the genetic signal shared between ELF5, severe COVID-19, and gene expression was specific to the lung." (PMID 35970849, 2022). "We next investigated ELF5 expression within the same tissues in samples from two patients who rapidly died from severe COVID-19 within ≤14 days." (PMID 35970849, 2022). "We validated the expression of ELF5 at the protein level in the different epithelial cells of the olfactory mucosa and lungs using immunofluorescence staining in non-COVID-19 samples." (PMID 35970849, 2022). "Among patients with a BMI less than 30 (non-obese patients), the rs7949972 ELF5 variant was associated with a reduced risk of severe COVID-19 (protective allele T, OR = 0.67, 95% CI = 0.47–0.95, p = 0.02, pbonf = 0.04)." (PMID 39175753, 2024). "Therefore, the objective of our study is to investigate genetic variants in the genes AQP3, ARHGAP27, ELF5, IFNAR2, LIMD1, OAS1 and UPK1A, which were selected due to the association of these genes with the severity of COVID-19, in a sample of Amazonian indigenous peoples." (PMID 38543725, 2024). "For rs7949972 ELF5, a protective effect against severe COVID-19 was observed in non-obese patients (effect allele T, OR = 0.67, 95% CI = 0.47–0.95, p = 0.02, (pbonf = 0.04)), improving thrombodynamic parameters (CS (p = 0.02), stationary spatial clot growth rates, Vst (p = 0.02))." (PMID 39175753, 2024). "Seven new genes (AQP3, ARHGAP27, ELF5, IFNAR2, LIMD1, OAS1 and UPK1A) were related to the severity of COVID-19 in populations of European origin." (PMID 38543725, 2024). "Another study developed in 34 Spanish hospitals with 11,939 positive cases of COVID-19 identified the relationship of the AQP3, ARHGAP27, ELF5, IFNAR2, LIMD1, OAS1 and UPK1A genes with the severity of the disease." (PMID 38543725, 2024). "However, recent research has highlighted its role in COVID-19, revealing that key host factors for SARS-CoV-2 (Ace2 and Tmprss4) are upregulated in Elf5-overexpressing AT2 cells." (PMID 39175753, 2024).